ASIC1 (acid sensing ion channel subunit 1)
Diseases named in the same sentence as ASIC1 in open-access papers (continued):
Sharing a sentence is not in itself a finding about the gene and the disease.
Primary Progressive MS (1 paper, 2019). "In autoptic brain tissues from patients affected by Primary Progressive MS (PPMS) upregulation of ASIC1 was also observed, and amiloride administration improved tissue lesions in PPMS thus exerting a neuroprotective effect, as indicated in a pilot trial." (PMID 30549327, 2019).
rheumatoid arthritis (1 paper, 2014). A chronic, systemic autoimmune disorder characterized by inflammation in the synovial membranes and articular surfaces. "Experiments were performed in cultured FLS from wild-type (WT) and ASIC3-/- mice, ASIC1-/- mice, and people with rheumatoid arthritis." (PMID 24923411, 2014).
Right ventricular hypertrophy (1 paper, 2018). In this case the right ventricle is more muscular than normal, causing a characteristic boot-shaped (coeur-en-sabot) appearance as seen on anterior- posterior chest x-rays. "However, Acid sensing ion channel 1 (ASIC1) is expressed in a variety of tissues including PASMC, whose contribute to enhanced Ca2+ entry mediating vasoconstriction, vascular remodeling, and right ventricular hypertrophy associated with hypoxic PH." (PMID 30322215, 2018).
synovitis (1 paper, 2014). Inflammation of a synovial membrane. "In synovitis, inflammatory mediators are released that can activate intracellular pathways to increase expression of ASIC3, decrease expression of ASIC1, increase (Ca2+)i, and increase phosphorylation of ERK." (PMID 24923411, 2014).
temporal lobe epilepsy (1 paper, 2025). A localization-related (focal) form of epilepsy characterized by recurrent seizures that arise from foci within the temporal lobe, most commonly from its mesial aspect. "This study is a systematic report concerning ASIC1 in temporal lobe epilepsy, including in vivo and in vitro experiments addressing both the acute and chronic phases." (PMID 40677921, 2025). "We also verified that ASIC1 is trafficked to the plasma membrane and regulated by the Rho/ROCK and PI3K signaling pathways in temporal lobe epilepsy." (PMID 40677921, 2025).
tumor (22 papers, 2010 to 2026). "The higher expression of ASIC1/ASIC3 was associated with poor tumor differentiation, advanced TNM stage, lymph node metastasis and distant metastasis." (PMID 28518134, 2017). "Our cell culture experiments revealed that mild acidification (pH 6.5) increased ASIC1 expression, but viability varied depending on the presence of the tumor supernatant." (PMID 40149892, 2025). "Our results showed that ASIC1 expression was significantly elevated in liver tumor tissues and correlated with tumor progression." (PMID 40149892, 2025). "Recent evidence supports that ASIC1 also participates in promoting tumor cell proliferation, migration, and survival in acidic environments." (PMID 40149892, 2025). "In this study, we examined ASIC1 expression in clinical liver tumor tissues using immunohistochemistry and immunofluorescence, correlating it with tumor stages." (PMID 40149892, 2025). "Immunohistochemical (IHC) staining demonstrated a progressive increase in ASIC1 expression across advancing tumor stages, with significantly higher ASIC1 levels observed in Stage III compared to earlier stages." (PMID 40149892, 2025). "Our immunofluorescence analysis of post-surgical liver tumor tissue samples revealed that ASIC1 expression was significantly upregulated in tumor tissues compared to adjacent non-tumor tissues." (PMID 40149892, 2025). "Among these genes, high expression of AMIGO2 and ASIC1 has been reported to promote tumor metastasis." (PMID 35022521, 2022). "In progression group, high expression of AMIGO2 and ASIC1 has been reported to promote tumor metastasis." (PMID 35022521, 2022). "The authors found that ASIC2 is not expressed in the plasma membrane of glial cells, whereas ASIC1 is indeed expressed on these tumor cells, analogous to our findings in BCC." (PMID 34199609, 2021). "Concerning the tumor tissues investigated in this study, ASIC1 is strongly expressed in SCC, BCC and in NCN in both epidermal and dermal portions." (PMID 34199609, 2021). "In a murine GC xenograft model, ASIC1 or ATG5 gene knockdown inhibited the growth of the tumor cells, whereas ASIC1 shRNA treatment led to decreased tumor volumes and prolonged survival times of the animals." (PMID 33856653, 2021). "To further determine the role of ASIC1 in castration resistance, we performed xenograft animal tumor models using castrated severe combined immunodeficiency male mice." (PMID 27941930, 2016). "Targeting ASIC1 or PFKM may represent a novel therapeutic strategy for disrupting tumor adaptation in liver malignancies." (PMID 40149892, 2025). "Taking these considerations and our results together, ASIC1 might serve as a potential therapeutic target, but further functional studies are required to fully understand the role of ASIC1 in tumor progression." (PMID 34199609, 2021). "In breast cancer cells, ASIC1 knockdown inhibits in vivo tumour growth and metastasis." (PMID 32575381, 2020). "Moreover, regulation of ROS production by ASIC1 is specific to acidosis-induced cell invasion and tumor growth." (PMID 27403419, 2016). "The acid-sensing ion channels ASIC1 and ASIC2, as well as the transient receptor potential vanilloid channels TRPV1 and TRPV4, are proton-gated cation channels that can be activated by low extracellular pH (pHe), which is a hallmark of the tumor microenvironment in solid tumors." (PMID 34199609, 2021). "The majority of cancer research has been on ASIC1, whereas the roles of ASIC2 and ASIC3 have been explored in only a limited number of studies, but they seem related to acidification of the tumor microenvironment." (PMID 41516419, 2026). "Upregulated ASIC1 and ASIC3 in prostate cancer cells promote in vitro migration and in vivo tumour metastasis." (PMID 32575381, 2020). "Some NCN show a decreasing ASIC1/2 expression in deeper dermal tumor tissue, while MM seem to not lose ASIC1/2 in deeper dermal portions." (PMID 34199609, 2021).
tumor (continued). "Some NCNs show a decreasing ASIC1/2 expression in deeper dermal tumor tissue, while MMs seem to not lose ASIC1/2 in deeper dermal portions." (PMID 34199609, 2021). "Future studies need to clarify the exact role of ASIC1 and ASIC3 in different tumours." (PMID 29057936, 2017). "In the present study, we show that ERK, one of mitogen-activated protein kinases (MAPKs), serves as an alternative pathway through which ASIC1 and NF-κB are connected, especially in cancer cells carrying constitutively active AKT, leading to tumor cell growth and invasion." (PMID 27941930, 2016). "However, no studies focus on the role of ASIC1 in neoplasia." (PMID 35207041, 2022). "According to them, ASIC1 and ASIC2 are co-expressed in normal cells, and the lack of ASIC2 in tumor cells leads to a large inward cation current." (PMID 34199609, 2021). "The role of ASIC1 and ASIC3 was further confirmed in-vivo, where a xenograft mouse model injected with BxPC-3 cells with a stable knockdown of ASIC1 and ASIC3 showed a significant decrease in lung and liver metastasis, but no obvious effect on tumor growth." (PMID 33178018, 2020). "Separate inhibition or knockdown of ASIC1 and ASIC3 decreased the acidity-promoted invasion and migration capacity of PDAC cell lines, but did not decrease the proliferation rate, suggesting that ASIC1 and ASIC3 are involved in the metastatic process of PDAC, but not tumor cell growth." (PMID 33178018, 2020).
cancer (15 papers, 2016 to 2026). A tumor composed of atypical neoplastic, often pleomorphic cells that invade other tissues. "ASICs and ENaC belong to the same channel family, and both ASIC1 and ENaC are acutely activated by acidic pH, and both channels are implicated in cancer development." (PMID 32764426, 2020). "We showed previously that apoptosis induction underlies the mambalgin-2 antiproliferative action in GBM cells, and propose here that the growth inhibition due to the apoptosis induction is common for the mambalgin-2 mediated ASIC1 inhibition in cancer cells." (PMID 34680442, 2021). "In line with the data obtained, the media acidification was shown to up-regulate the ASIC1 expression in breast and colorectal cancer cells." (PMID 34680442, 2021). "Given the importance to ERK and NF-κB in cancer, we tested the effect of ASIC1 KO on cell invasion by transwell invasion assays." (PMID 27941930, 2016). "ASIC1 subunits also function similarly in promoting cancer cell migration." (PMID 27403419, 2016). "Thus, a key question is whether ASIC1-mediated cell signaling still takes place in the cancer cells carrying constitutively active AKT." (PMID 27941930, 2016). "Therefore, this ASIC1-ROS-ERK-IκBα-NF-κB axis may provide an opportunity for intervention in cancer therapy." (PMID 27941930, 2016). "Psalmotoxin 1 (PcTX1) is a blocker of the ASIC isoforms ASIC1 and ASIC2, which have been shown to promote the proliferative and migratory effects of extracellular acidosis on cancer cells." (PMID 34067971, 2021).
neurodegenerative disease (2 papers, 2022). A disorder of the central nervous system characterized by gradual and progressive loss of neural tissue and neurologic function. "From a pathological standpoint, ASIC1 in oligodendrocytes has been shown to play a major role in neurodegenerative diseases, specifically in MS." (PMID 35207041, 2022). "MS is the primary neurodegenerative disease related to ASIC1 in oligodendrocytes." (PMID 35207041, 2022).
adenocarcinoma (1 paper, 2022). A common cancer characterized by the presence of malignant glandular cells. "Analysis of the samples from the patients with adenocarcinoma at stages II–IV by the Kaplan–Meier method showed that the patients with a lower expression of mRNA coding the ASIC1 and γ-ENaC subunits demonstrated the better survival prognosis." (PMID 35837090, 2022).
prostate (1 paper, 2016). "Together, these results support the significance of ASIC1-ROS-ERK-IκBα-NF-κB axis in prostate tumorigenesis, especially in the constitutively active AKT background." (PMID 27941930, 2016).
ASIC1 also shares sentences with these, for which no sentence is quoted: ischemia (4 papers); neurological disorders (4); Acidosis (3); Parkinson disease (3); depression (2); gastric cancer (2); leukemia (2); panic disorder (2); Alzheimer disease (1); amyotrophic lateral sclerosis (1); Arthritis (1); asthma (1); basal cell carcinoma (1); Bradycardia (1); cerebral edema (1); Cerebral ischemia (1); cognitive decline (1); Cognitive impairment (1); demyelinating disease (1); disc degeneration (1); endothelial dysfunction (1); generalized anxiety disorder (1); head and neck cancer (1); heart failure (1); hematoma (1); hepatocellular carcinoma (1); Hypertension (1); infection (1); interstitial cystitis (1); limb ischemia (1).
A further 12 diseases each share a sentence with ASIC1 in 1 paper.